PPP1R1A (protein phosphatase 1 regulatory inhibitor subunit 1A)
Description:
Inhibitor of protein-phosphatase 1. This protein may be important in hormonal control of glycogen metabolism. Hormones that elevate intracellular cAMP increase I-1 activity in many tissues. I-1 activation may impose cAMP control over proteins that are not directly phosphorylated by PKA. Following a rise in intracellular calcium, I-1 is inactivated by calcineurin (or PP2B). Does not inhibit type-2 phosphatases.
Synonyms: IPP1; I1
Tractability: PROTAC: its protein half-life has been measured.
Gene: Protein-coding gene on chromosome 12 (54,575,387 to 54,588,659, reverse strand). Ensembl gene ENSG00000135447.
Gene Ontology:
Molecular function: protein binding; protein serine/threonine phosphatase inhibitor activity; protein phosphatase inhibitor activity
Biological process: intracellular signal transduction; signal transduction
Cellular component: cytoplasm
Genetic constraint (gnomAD): Loss-of-function variants: 18 observed, 21 expected, observed/expected ratio (o/e) 0.86, 90% interval 0.59 to 1.27. The upper end of that interval is the gene's LOEUF score, 1.27, which puts it in group 5 of 6, group 1 being the genes least tolerant of losing a copy. Missense variants: 207 observed, 206.63 expected, observed/expected ratio (o/e) 1, 90% interval 0.89 to 1.12. Synonymous variants: 84 observed, 71.58 expected, observed/expected ratio (o/e) 1.17, 90% interval 0.98 to 1.41.
Homologues: Orthologues: chimpanzee PPP1R1A (99% identical), guinea pig PPP1R1A (85% identical), macaque PPP1R1A (82% identical), rat Ppp1r1a (81% identical), mouse Ppp1r1a (80% identical), dog PPP1R1A (74% identical), pig PPP1R1A (68% identical), tropical clawed frog ppp1r1a (49% identical). Paralogues in human: PPP1R1B (30% identical), PPP1R1C (30% identical).
Diseases named in the same sentence as PPP1R1A in open-access papers:
PPP1R1A is named in the same sentence as 17 diseases in open-access papers, as found by Europe PMC text mining. Sharing a sentence is not in itself a finding about the gene and the disease. The quoted sentences say what the papers report.
Ewing sarcoma (6 papers, 2019 to 2025). A small round cell tumor that lacks morphologic, immunohistochemical, and electron microscopic evidence of neuroectodermal differentiation. "PPP1R1A, an inhibitor of protein phosphatase-1, is associated with oncogenic effects and is commonly implicated in the progression and metastasis of Ewing's sarcoma." (PMID 40432804, 2025). "The effect of PPP1R1A on the progression and metastasis of Ewing’s sarcoma has previously been described." (PMID 37596405, 2023). "Inhibition of PPP1 by the regulatory subunit PPP1R1A in Ewing sarcoma has been shown to promote tumour growth and metastasis." (PMID 31019223, 2019). "mRNA expression of PPP1R1A, GLI1, FoxM1, and NR0B1 genes highly expressed in Ewing’s sarcoma cells was dependent on EWS-FLI1." (PMID 36194562, 2022). "Interestingly, the expression of another sensitivity marker, PPP1R1A (protein phosphatase 1 regulatory subunit), has recently been reported to be induced by EWS/FLI in Ewing sarcoma lines as well (Fig. EV4D)." (PMID 38177929, 2024).
breast carcinoma (2 papers, 2022). "As a potential target of breast cancer, the expression level of PPP1R1A is closely related to the invasion and metastasis of breast cancer." (PMID 36003341, 2022). "Conversely, levels of PPP1R1A were reduced in breast cancer when compared to adjacent non-diseased breast tissue." (PMID 35982973, 2022).
colorectal cancer (2 papers, 2018 to 2025). A primary or metastatic malignant neoplasm that affects the colon or rectum. "Differential expression of PPP1R1A was often observed in non-small cell lung cancers and colorectal cancers." (PMID 30390627, 2018). "However, evidence of PPP1R1A's impact on colorectal cancer remains elusive and requires further investigation." (PMID 40432804, 2025).
atherosclerosis (1 paper, 2024). A disease characterized by the build-up of fatty material and calcium deposition in the arterial wall resulting in partial or complete occlusion of the arterial lumen. "In addition, GSTA4, RAPGEF3, TRPV4, INSIG1, UTS2, and PPP1R1A all play a role in the development of atherosclerosis." (PMID 39758846, 2024).
insulinoma (1 paper, 2018). "Silencing of either Arg2 or Ppp1r1a in insulinoma INS-1 832/13 cells reduced insulin secretion, while the opposite was observed by silencing Tmem37, consistent with the latter being an inhibitory subunit of voltage-gated calcium channels." (PMID 29185012, 2018).
type 2 diabetes (1 paper, 2018). "Analysis of islet alpha and beta cell-enriched fractions from five non-diabetic and four type 2 diabetic OD by RT-qPCR showed that ARG2, PPP1R1A and TMEM37 were enriched in beta cells and downregulated in type 2 diabetes." (PMID 29185012, 2018).
tumor (9 papers, 2018 to 2024). "Many of the mutated genes, such as NOX4 and PPP1R1A, have been implicated in tumour progression and/or metastasis." (PMID 34299215, 2021). "The role of PP1 regulatory subunit 1A (PPP1R1A), also called inhibitor-1, has been shown in tumor development." (PMID 38999976, 2024). "In EwS, in addition to reduce the tumor progression, PPP1R1A knockdown reduced the metastases of xenografted EwS tumors, indicating that PPP1R1A can be used as a therapeutic target for metastasis treatment." (PMID 36230825, 2022). "PPP1R1A depletion or a small molecule inhibitor of the PKA/PPP1R1A/PP1 cascade decreased tumor growth and metastasis in an ES orthotopic xenograft mouse model." (PMID 32477459, 2020). "For example, gene PPP1R1A with a small FC of 0.97 but a large aGRP of 0.39 on the Selamat’s data is a tumor promoter, whose depletion can significantly suppress oncogenic transformation and cell migration." (PMID 30390627, 2018). "More importantly, the discovery of the novel role of PPP1R1A in ES cell cycle modulation led us to test a rational combinatorial therapeutic strategy that is effective not only in limiting cell viability and tumor growth, but also cell migration and tumor metastasis." (PMID 32477459, 2020). "We previously demonstrated that PPP1R1A is an important EWS/FLI target gene and plays a critical role in ES pathogenesis by promoting ES tumor growth and metastasis via the PKA/PPP1R1A/PP1 pathway." (PMID 32477459, 2020). "We found that combinatorial therapy of PPP1R1A inhibition with an IGF-1R inhibitor was more effective not only in limiting primary xenograft tumor growth, but also in decreasing lung metastasis, demonstrating a promising specific strategy to treat both primary and metastatic ES." (PMID 32477459, 2020). "Importantly, we demonstrate a synergistic/additive effect of the combinatorial therapy of PPP1R1A and insulin-like growth factor 1 receptor (IGF-1R) inhibition on decreasing ES cell proliferation and migration in vitro and limiting xenograft tumor growth and metastasis in vivo." (PMID 32477459, 2020). "In the current study, we found that combinatorial therapy of PPP1R1A and IGF-1R inhibitors is superior to single treatment not only in limiting tumor growth but also lung metastasis which has never been reported in prior studies." (PMID 32477459, 2020).
PPP1R1A also shares sentences with these, for which no sentence is quoted: heart failure (3 papers); cancer (2); non-small cell lung carcinoma (2); Anxiety (1); cardiomyopathy (1); depression (1); gastric cancer (1); heart disease (1); Insulin resistance (1); nasopharyngeal carcinoma (1).